IFI27 (interferon alpha inducible protein 27)
Description:
Probable adapter protein involved in different biological processes. Part of the signaling pathways that lead to apoptosis. Involved in type-I interferon-induced apoptosis characterized by a rapid and robust release of cytochrome C from the mitochondria and activation of BAX and caspases 2, 3, 6, 8 and 9. Also functions in TNFSF10-induced apoptosis. May also have a function in the nucleus, where it may be involved in the interferon-induced negative regulation of the transcriptional activity of NR4A1, NR4A2 and NR4A3 through the enhancement of XPO1-mediated nuclear export of these nuclear receptors. May thereby play a role in the vascular response to injury (By similarity). In the innate immune response, has an antiviral activity towards hepatitis C virus/HCV. May prevent the replication of the virus by recruiting both the hepatitis C virus non-structural protein 5A/NS5A and the ubiquitination machinery via SKP2, promoting the ubiquitin-mediated proteasomal degradation of NS5A. Also promotes virus-induced pyroptosis by activating CASP3 in the mitochondria after 'Lys-6'-linked ubiquitination by TRIM21.
Synonyms: p27; ISG12A; FAM14D; ISG12
Tractability: Antibody: UniProt predicts a signal peptide or a membrane-spanning region. PROTAC: UniProt records ubiquitination sites on it.
Gene: Protein-coding gene on chromosome 14 (94,104,836 to 94,116,700, forward strand). Ensembl gene ENSG00000165949.
Subcellular location: Mitochondrion membrane; Nucleus inner membrane; Endoplasmic reticulum membrane
Pathways (Reactome):
Immune System: Interferon alpha/beta signaling; Modulation of host responses by IFN-stimulated genes
Gene Ontology:
Molecular function: identical protein binding; lamin binding; molecular adaptor activity; protein binding; RNA polymerase II-specific DNA-binding transcription factor binding
Biological process: apoptotic process; defense response to virus; extrinsic apoptotic signaling pathway; host-mediated perturbation of viral genome replication; innate immune response; negative regulation of transcription by RNA polymerase II; proteasome-mediated ubiquitin-dependent protein catabolic process; protein K48-linked ubiquitination; pyroptotic inflammatory response; regulation of protein export from nucleus; type I interferon-mediated signaling pathway; intrinsic apoptotic signaling pathway
Cellular component: endoplasmic reticulum membrane; mitochondrial membrane; mitochondrion; nuclear envelope; nuclear inner membrane; mitochondrial outer membrane; membrane
Genetic constraint (gnomAD): Loss-of-function variants: 2 observed, 8.01 expected, observed/expected ratio (o/e) 0.25, 90% interval 0.1 to 0.79. That is too few expected variants to judge how well the gene tolerates losing a copy. Missense variants: 145 observed, 146.83 expected, observed/expected ratio (o/e) 0.99, 90% interval 0.86 to 1.13. Synonymous variants: 66 observed, 63.66 expected, observed/expected ratio (o/e) 1.04, 90% interval 0.85 to 1.27.
Homologues: Orthologues: chimpanzee IFI27 (98% identical), macaque IFI27 (69% identical), zebrafish ifi27.6 (36% identical), zebrafish ifi27.4 (35% identical). Paralogues in human: IFI27L1 (48% identical), IFI27L2 (48% identical), IFI6 (33% identical).
Diseases named in the same sentence as IFI27 in open-access papers:
IFI27 is named in the same sentence as 138 diseases in open-access papers, as found by Europe PMC text mining. Sharing a sentence is not in itself a finding about the gene and the disease. The quoted sentences say what the papers report.
viral infection (61 papers, 2008 to 2025). "IFI27 has been recognized as a biomarker for early Sars-CoV-2 infection, corroborating the association with viral infections." (PMID 40963624, 2025). "Several ISGs, such as MxA, ISG15 and IFI27, exhibit unique expression patterns and robust diagnostic performance in identifying viral infections." (PMID 39861921, 2025). "The protein coded by IFI27 was previously shown to be associated with other viral infections, including Hepatitis C, respiratory syncytial virus (RSV) infection, and Enterovirus 71 (EV71) hand, foot, and mouth disease." (PMID 40476695, 2025). "This aligns with findings in other viral infections, where IFI27 is implicated in immune response modulation and viral replication control." (PMID 39282474, 2024). "In particular, IFI27 was positively linked to M1 macrophage, which is considered an active mediator of virus infection-associated myositis." (PMID 37638007, 2023). "In this regard, we see key subsets of immune related genes that are up-regulated by AZA with potential for inhibiting tumor growth including IFI27, which encodes a protein triggering apoptosis in late stages of chronic viral infection." (PMID 24162015, 2013). "This new function of IFI27 could be used to design target-driven compounds to treat diseases associated with an exacerbated induction of innate immune responses and to inhibit viral infections, such as SARS-CoV-2." (PMID 39431052, 2024). "While we did not identify an inflammatory signature in our keratinocyte cultures, SERCA2-deficient cells had reduced IFI27 and other interferon response genes, which might explain the susceptibility of DD lesions to viral infection." (PMID 37561594, 2023). "They had upregulated IFI27, a type-I interferon-induced gene commonly upregulated during viral infection and other inflammatory responses, and recently suggested as a target for immunoregulatory therapies." (PMID 40806258, 2025). "Our five genes included three genes overexpressed in bacterial infections (LCN2, PI3, and SLPI) and two overexpressed in viral infections (IFI27 and IFIT2)." (PMID 40843077, 2025). "IFI27 is upregulated in blood samples during viral infections and has emerged as a robust single-gene biomarker." (PMID 39861921, 2025). "Previously, we showed that IFI27 negatively modulates the innate immune responses induced after viral infections, by modulating RIG-I and MDA5 activation." (PMID 40522981, 2025). "We found that a threshold of ΔCq = 74 for the research assay and VITA Index = 6.9 for the InSignia assay provided the most optimal level of IFI27 expression to differentiate between viral and non-viral infections." (PMID 40593901, 2025). "In this context, IFI27 has been thoroughly validated as a blood biomarker for viral infections using RNA only as template and qPCR utilising TaqMan probes, with the diagnostic threshold of ΔCq = 74 obtained in this study aligning with prior research findings." (PMID 40593901, 2025). "The corresponding gene expression signature reflected the immune response to the viral infection dominated by a prominent type I interferon, with IFI27 among the most over-expressed genes." (PMID 38772950, 2024). "This validation by MAS in identifying IFI27 is significant, as it indicates the gene's involvement in crucial biological pathways during severe viral infections." (PMID 39282474, 2024). "Supporting this selection of IFI27, several studies have provided insights into its role in different viral infections." (PMID 39282474, 2024). "The pathway analysis of IFI27, therefore, offers a more nuanced view of its role, extending beyond mere gene expression to its functional implications in the context of viral infections and immune system responses." (PMID 39282474, 2024). "VirSig was defined as the signature of the host response to viral infection using the average expression of five representative genes, including IFI27, RSAD2, IFI44L, ISG15 and IFITM3." (PMID 38790931, 2024).
viral infection (continued). "IFI27 has been pinpointed as a central gene in the immune response to viral infection, as evidenced by its involvement in the “cytokine-mediated signaling pathway” (GO:0019221) and “response to type I interferon” (GO:0034340)." (PMID 39282474, 2024). "The convergence of findings from various studies establishes IFI27 as a critical gene in the context of viral infections, highlighting its significant role across different viral diseases." (PMID 39282474, 2024). "In vitro studies have shown that IFI27 is up-regulated in plasmacytoid dendritic cells, which are antigen-presenting cells sensitive to viral infection." (PMID 37007526, 2023). "IFI27 is one of the key downstream targets of interferon response to viral infections and dsRNA-mediated viral mimicry, leading to the induction of an antiviral state causing cell cycle arrest." (PMID 37024521, 2023). "As an innate immune effector, ISG12a (also known as IFI27) promotes an innate immune response to viral infections." (PMID 37190239, 2023). "As one of the mentioned six genes, and as a general noticeable player in infectious diseases, the function of IFI27 as part of the innate immune response in connection with viral diseases has also been reported in diverse organisms, including mice and chicken." (PMID 35220956, 2022). "Understanding the exact mechanisms by which IFI27 influences Ebola pathogenesis could pave the way for novel approaches to manage and treat this severe viral infection." (PMID 39282474, 2024). "Although innate immune responses are beneficial to combat viral infections, exacerbated inflammatory responses after viral infections are detrimental to the host, so, in this sense, IFI27 could prevent exacerbated innate immune responses to viral infections." (PMID 37187533, 2023). "However, it has not been clearly defined its biological importance as well as the mechanisms by which IFI27 participates in the innate immune response as an ISG during viral infection." (PMID 37187533, 2023). "The function of IFI27 is further illustrated in the case of viral infection." (PMID 35974384, 2022). "IFI27 is a member of the interferon alpha inducible proteins that may participate in the pathogenesis of various viral infections." (PMID 33388093, 2021). "The second key driver is IFN beta as well as IFN alpha (interferon type I) for upregulating the expression of IFI27, with greater magnitude in viral than in bacterial infection; type I interferons are produced by fibroblasts and monocytes when a viral infection is recognized." (PMID 34442377, 2021). "By now, many researches about IFI27 focus on the connective tissue diseases and tumors whereas the studies regarding the correlation between IFI27 expression and viral infectious diseases are inadequate, therefore, it is meaningful and worthful to pay more attention on this topic." (PMID 33388093, 2021). "We found that IFI27 levels were significantly elevated in those with confirmed respiratory viral infection (mean fold change = 483), confirming the presence of an immune response to the viral infection." (PMID 29666961, 2018). "Interferon is a cytokine that protects cells from viral infection and the upregulated expression of IFI27 and IFI6 might be a protective response of cancer cells to certain stresses, as well as to the upregulation of HSP expression." (PMID 27629773, 2016). "Third, given our results suggesting that interferon treatment increased IFI27 expression, viral infection might have some influence on IFI27 level (case DIGI1)." (PMID 27100186, 2016). "However, in addition to the functions of IFI6 and IFI27 in apoptosis, roles in viral infections have also been suggested." (PMID 23894493, 2013). "Therefore, IFI27 expression was discussed as biomarker for viral infections." (PMID 35220956, 2022).
viral infection (continued). "This correlation between the levels of IFI27-HA and RLuc, further show the ability of IFI27 to induce PKR and eIF2α phosphorylation, and further promote host shut-off after viral infections, being this effect dose-dependent." (PMID 40522981, 2025). "Many of the genes corresponding to this factor such as IFI27, ISG15, IFITM3 are parts of the type 1 interferon signaling pathway normally observed in viral infections." (PMID 39369208, 2024). "Previously we showed that IFI27 positively affects SARS-CoV-2 and IAV replication by negatively modulating the antiviral responses induced after viral infections." (PMID 39431052, 2024). "In the context of dual influences from immunosuppression and viral infection, KTRs exhibited more specific plasma cells, along with significant enrichment of dysfunctional GZMB and XAF1 double-positive effector T cells and IFI27-positive monocytes." (PMID 38238762, 2024). "Taken together, the larger effect size between COVID-19 and healthy controls as well as the higher expression levels in monocytes suggested that IFI27 and SIGLEC1 is a monocyte-specific biomarker with slightly different property in response to viral infection." (PMID 38268924, 2023). "The 8-gene signature included three genes over-expressed in bacterial infections (SMARCD3, ICAM1, EBI3; “bacterial genes”) and five over-expressed in viral infections (JUP, SUCLG2, IFI27, FCER1A, HESX1; “viral genes”)." (PMID 36543117, 2022). "The top genes in the individual LIMMA analyses that were differentially expressed in peripheral blood samples of patients hospitalized with viral infection vs. bacterial (baseline in the model) infection were ISG15, TIMM10, IFI27, IFI44L and OAS2." (PMID 34593881, 2021). "The initial defense and adaptive immune responses against viral infection are performed by type I IFNs (IFN-α/β) such as RTP4, GBP1, OAS1, IFI27, and IF44L." (PMID 31665046, 2019). "Actually, we identified that LCN2, PI3, and SLPI were up-regulated in bacterial infections, and IFI27 and IFIT2 were up-regulated in viral infections in the study, which may be helpful in assisting with the diagnosis of B/V co-infection in children." (PMID 40843077, 2025). "Moreover, previous studies have implicatedsimilar ISGs, including OASL, IFI27, IFIT1 and IFI44L, in the pathogenesis of other viral infections such as hepatitis C virus (HCV),suggesting a broader role for these genes in viral-induced liver diseases." (PMID 40322700, 2025). "Additionally, BNIP3L was elevated in bacterial infection, potentially reflecting its role in mitophagy, while DNMT1, IFI27, SLFN5, and AHNAK were elevated in viral infection, and PABPC4 was elevated in KD." (PMID 39240972, 2024). "IFI27 is suggested to regulate the innate immune response during SARS-CoV-2 infection by interfering with the RIG-1 pathway, which is critical for recognizing viral infection and preventing hyper-inflammation and excessive innate immune responses." (PMID 39575237, 2024). "Indeed, many interferon‐related genes upregulated during viral infection in rats were found to be downregulated by PTS in this study (e.g., Oas1a, Oas2, Irf7, Ifi27, Lgals3 bp)." (PMID 39562169, 2024). "The data indicating that IFI27 negatively affects MDA5 activation after SARS-CoV-2 infection and poly(I:C) transfection, suggests that this effect is likely broader, impairing MDA5 activation after different viral infections." (PMID 39431052, 2024). "‘Interferon Alpha inducible protein 27 (IFI27)’, a known biomarker gene for influenza infection, is reported to be hypo methylated during COVID-19 infection, which alters the innate immune response upon viral infection." (PMID 36906872, 2023). "Although IFI27 is known to be upregulated during viral infections, the correlation between IFI27 and VL temporal trajectories has not been established prior to this study." (PMID 38038134, 2023).
viral infection (continued). "We speculate that IFI27, BST2, MX1 and ISG15 may play an important role in the suppression of ZIKV and other viral infections rendered by NS4A." (PMID 35522620, 2022). "Of the viral genes, IFI27 and JUP are known to be upregulated in response to viral infection." (PMID 36543117, 2022). "IFNα-inducible protein 6 (IFI6, aka IFI-6-16, or GIP3) is a member of a conserved protein family that consists of IFI6, IFI27 (ISG12a), IFI27L1 (ISG12c), and IFI27L2 (ISG12b), and it was first characterized as a cellular gene induced by the IFN response and virus infections." (PMID 34205058, 2021). "Our results demonstrate that genes related to important immune pathways such as antigen presentation, inflammation, apoptosis and response to virus (Cxcl10, CxCl11, Ccl5, Ifr7, Ifi27 Oas1b, Fcerg1,Mif, Clusterin and MHC class II) were upregulated as a result of virus infection." (PMID 18558011, 2008). "The majority of genes upregulated in HCV tumor-adjacent tissue, except IFI27, IFI6, and PLA2G2A, show average expression below 1 TPM in GTEx normal liver samples, suggesting that the upregulation of these immune-related genes in HCV tumor-adjacent tissue is likely mediated by the viral infection." (PMID 39005337, 2024). "Furthermore, there are several studies that demonstrate that IFI27 plays a role in viral infections, with either negative or positive effects on viral disease progression depending on the study and type of infection." (PMID 37187533, 2023). "The authors did, however, detect DMRs in another interferon-induced gene, ‘interferon alpha inducible protein 27’ (IFI27), as well as in ‘2′-5′-oligoadenylate synthetase 2’ (OAS2) which is a member of the 2–5 A synthetase family known to be involved in the innate immune response to viral infection." (PMID 35798818, 2022). "Actually, as a member of the interferon alpha inducible proteins, IFI27 may participate in the pathogenesis of various viral infections not solely limited in RSV infection." (PMID 33388093, 2021).